MTOR (mechanistic target of rapamycin kinase)
Diseases named in the same sentence as MTOR in open-access papers (continued):
Sharing a sentence is not in itself a finding about the gene and the disease.
breast cancer (continued). "Along this line, chemotherapy treatment of ruthenium and phloretin intricated enhanced cell death in breast carcinoma conditions and promoted Bcl2 and Bax by interrupting PI3K/Akt/mTOR signaling." (PMID 40761486, 2025). "In another study on HER2-positive breast cancer, aloe-emodin (AE) extracted from rhubarb roots showed the ability to suppress the ILK/AKT/mTOR axis and thus reduce YBX1 expression and elicit positive anticancer activity." (PMID 38255791, 2024). "Overall, the reconstructed protein signaling network comprehensively covered multiple breast cancer growth and proliferation pathways, including the PI3K-AKT, MTOR, apoptosis, ERBB, MAPK, and FOXO signaling pathways." (PMID 38394152, 2024). "A constitutively active mutant S473D Akt1 (caAkt1) restored Akt-mTOR activation and counteracted the proliferation inhibition and apoptosis induced by REG3A knockdown in breast cancer cells." (PMID 38840145, 2024). "The ethanolic extract of Z. nummularia significantly upregulated phosphorylated Akt and mTOR proteins in KAIMRC2 breast cancer cells, thus switching on the AKT/mTOR pathway, which is traditionally known to promote cell survival." (PMID 38531974, 2024). "This study demonstrated how exposure to FSS results in phosphor-protein changes in ER+ breast cancer cells, specifically enhanced phosphorylation of proteins in the AKT/mTOR signaling pathway." (PMID 38370397, 2024). "In breast cancer cells, ZKSCAN3 elevates migration and invasion abilities through the Akt/mTOR signaling pathway by suppressing p-Akt and p-mTOR expression, thereby promoting proliferation, migration, and invasion." (PMID 39519085, 2024). "In breast cancer, knockdown of BCAT1 eliminates BCAA catabolism, which inhibits mTOR-mediated mitochondrial biogenesis and function, repressing cancer proliferation." (PMID 38305803, 2024). "Everolimus, an mTOR inhibitor, was evaluated in the BOLERO-1 trial as a first-line treatment for advanced HER2+ breast cancer." (PMID 38256428, 2024). "This signaling pathway, in part, inhibits mTOR via AMPK activation, and is believed to be responsible for the inhibition of breast cancer cell proliferation, suppression of the G1 phase of the cell cycle, and induction of apoptosis." (PMID 38595915, 2024). "Surprisingly, the VD3-GNP treatment is found to downregulate ETV7, the PI3K/mTOR/AKT cascade, along with the HIPPO pathway’s key proteins YAP and TAZ, which indicates its importance in controlling breast cancer aggressiveness." (PMID 38791386, 2024). "In tamoxifen-resistant breast cancer, luteolin promotes cell apoptosis by suppressing the PI3K/AKT/mTOR pathway." (PMID 39584140, 2024). "Currently, both mTOR inhibitors and inhibitors to upstream mTOR mediators, such as RET, are candidate therapies for metastatic HR+ breast cancer." (PMID 39000231, 2024). "Various endocrine therapy strategies, including SERD, SERM, AI, GnRHa, and inhibitors of PI3K, AKT, mTOR, and CDK4/6, are being explored to enhance the immune response in breast cancer." (PMID 39188717, 2024). "This is a significant finding as previous studies have shown that echinacoside directly inhibits the PI3K/mTOR pathway in different cancer types, such as HCC, breast cancer, Ehrlich carcinoma, colorectal cancer, and ovarian cancer." (PMID 38461536, 2024). "It was seen through different databases that HMMR was highly upregulated in various malignancies, including breast cancer, and HMMR has a correlation with AURKA, TPX2, and CDK1, which are also involved in the upregulation of mTOR signaling pathways." (PMID 38576486, 2024). "The mechanistic target of rapamycin (mTOR) acts downstream of the phosphatidylinositol-3-kinase (PI3K)/Akt/mTOR pathway and plays a central role in breast cancer." (PMID 39594738, 2024).
breast cancer (continued). "These pathways included ‘IL-17 signaling’, ‘JAK-STAT signaling’, ‘mTOR signaling’, ‘PI3K-Akt signaling’, ‘MAPK signaling’, ‘Ras signaling’, ‘TGFbeta signaling’, ‘breast cancer’ and, most notably, ‘signaling pathways regulating pluripotency of stem cells’." (PMID 38886378, 2024). "With increasing doses of harmine, Bax is upregulated in breast cancer cells, whereas Bcl-2, p-AKT, p-mTOR, and p-Erk are downregulated." (PMID 38590646, 2024). "The lncRNA DUXAP8, transcribed from a pseudogene, modulates both the P3K/AKT/mTOR pathway and the EZH2-E-cadherin/RHOB pathways to exert its role in inducing breast cancer radioresistance." (PMID 39346726, 2024). "Nevertheless, in breast cancer and lung cancer cells, paclitaxel activates AMPK, inhibits mTOR signaling and increases apoptosis." (PMID 39584140, 2024). "Everolimus, an mTOR inhibitor, when combined with endocrine therapy, has been shown to improve PFS in patients with breast cancer." (PMID 38791958, 2024). "In breast cancer, enhancement of the PI3K/Akt/mTOR signaling pathway promotes cell proliferation and inhibits cell apoptosis." (PMID 39742381, 2024). "A well-known example is the recently approved triplet therapy for ER+/HER2- breast cancer, which includes a CDK4/6 inhibitor, a PI3K/AKT/mTOR inhibitor, and endocrine therapy." (PMID 39501277, 2024). "To determine the role of MARCH1 in the mTOR signaling pathway, we constructed the MARCH1 knocked-down breast cancer cell line." (PMID 39061024, 2024). "Netupitant inhibits the activation of the PI3K/AKT/mTOR signaling pathway by suppressing the AGK protein, inducing the apoptosis of breast cancer cells." (PMID 39594764, 2024). "In breast cancer such as TNBC, AURKB overexpression can promote EMT by activating the AKT/mTOR signaling pathway." (PMID 38886738, 2024). "In observational human breast cancer studies, increased E-cadherin immunoreactivity due to increased E-cad/NTF-1 but both decreased Ki-67 and mTOR activity was observed selectively and differentially within the lymphovascular tumor emboli." (PMID 39392391, 2024). "Additionally, mTOR inhibitors have demonstrated favorable outcomes in combination therapies for head and neck cancer, as monotherapy in esophagogastric cancer, and in estrogen receptor-positive (ER+) breast cancer patients after aromatase inhibitor (AI) failure." (PMID 39796034, 2024). "In breast cancer, phosphorylated AKT promoted tumor cell proliferation and cell cycle progression by activating the mTOR complex." (PMID 38914958, 2024). "In breast cancer, dysregulation of the PI3K/AKT/mTOR pathway occurs through several mechanisms, such as increased PI3K activity, loss of inhibitory functions, or mutations in tumor suppressor genes like INPP4B and PTEN." (PMID 39850811, 2024). "In breast cancer, the PI3K/Akt/mTOR pathway, commonly activated in tumor cells, generally suppresses autophagy, promoting survival and resistance to chemotherapy." (PMID 39655055, 2024). "Study limitations the presence of SGLT2 in breast cancer and the expression of AMPK/mTOR are crucial factors for investigating the mechanism of action of the combination, which was not examined in the present study." (PMID 38686050, 2024). "Everolimus (C53H83NO14) is an effective anti-cancer drug for human breast cancer, inhibiting the growth and aggressiveness of breast cancer cells through the PI3K/AKT/mTOR pathways." (PMID 39768828, 2024). "Extensive interaction between the Hippo pathway and PI3K/AKT/mTOR promotes cell proliferation, migration, and aggressiveness in breast cancers; induces miR-29 to inhibit PTEN; and promotes the PI3K-mTOR pathway to regulate tissue growth and hyperplasia." (PMID 38791386, 2024). "The importance of targeting the PI3K/Akt pathway in breast cancer has led to the investigation of potential PI3K and mTOR inhibitors to act synergistically with chemotherapy or hormone therapy." (PMID 38672636, 2024).
breast cancer (continued). "MEDAG has been shown to regulate breast cancer (BC) progression and EMT via the AKT/AMPK/mTOR pathway, reducing chemosensitivity in BC cells." (PMID 38717641, 2024). "Within breast carcinoma, OGN suppresses the capacity of tumor cells to proliferate and invade through the PI3K/Akt/mTOR signaling." (PMID 38402185, 2024). "The dysregulation of cell signaling pathways, notably the PI3K/AKT/mTOR (PAM) pathway, significantly contributes to tumor cell proliferation and therapy resistance across a range of malignancies, encompassing breast cancer as well." (PMID 38504785, 2024). "In breast cancer and colon cancer, OTUD5 promotes carcinogenesis by regulating the mammalian target of rapamycin (mTOR) and Hippo signaling pathways." (PMID 37190070, 2023). "In breast cancer, OTUD3 stabilizes PTEN, inhibiting the PI3K/p-AKT/mTOR pathway and suppressing tumor growth." (PMID 38288086, 2023). "GSEA analysis revealed that in breast cancer patients with elevated CDCA5 expression, the PI3K/AKT/mTOR pathway was abnormally activated." (PMID 37287817, 2023). "Conversely, in ER− breast cancer, inhibition of class I PI3K and/or mTOR leads to Wnt/β-catenin activation." (PMID 37471270, 2023). "HMGB3 inhibition inhibits colony formation and induces apoptosis by increasing reactive oxygen species accumulation and decreasing MMP, p-mTOR, and STAT3 levels in human breast cancer cells." (PMID 37328851, 2023). "MiR-216b potentiates breast cancer cell autophagy and apoptosis in vitro by targeting HK2 through the mTOR signaling pathway." (PMID 37019900, 2023). "Several studies have reported that PI3K, MEK, mTOR, and HDAC inhibitors are able to synergize with BET inhibitors in breast cancer cells." (PMID 37686632, 2023). "As for SCH772984, enhanced effects were reported in response to triple combinations, as in breast cancer cells treated with SCH772984, ABT-737, and HER-2 inhibitors, or in acute myeloid leukemia cells treated with SCH772984, ABT-199, and PI3K/mTOR inhibitors." (PMID 36902392, 2023). "mTOR signaling pathways, which include Akt and PI3K, are among the most commonly altered pathways leading to tumorigenesis in breast cancer." (PMID 37904250, 2023). "Dual PI3K and mTOR inhibitors, such as BEZ-235, have been used in studies on colorectal and breast cancer." (PMID 37097377, 2023). "In breast cancer, CBD-induced apoptosis is accompanied by down-regulation of the mammalian target of rapamycin (mTOR), which regulates cell proliferation and apoptosis, cell cycle, and localization of PPARγ in the nuclei and cytoplasmic of the tested cells." (PMID 37630232, 2023). "FBXW7 liberation from C/EBPδ transcriptional repression promotes polyubiquitination of endogenous mTOR and HIF-1α protein binding and inhibits intracellular accumulation, reducing lung metastasis in breast cancer model mice under hypoxic adaptation." (PMID 37658431, 2023). "Human epidermal growth factor receptor 2 (HER-2), overexpressed in breast cancer, promotes tumor cell proliferation and invasion by activating the phosphatidylinositol 3-kinase (PI3K)/Akt/mammalian rapamycin target (mTOR) pathway." (PMID 36986711, 2023). "For instance, in breast cancer, DCA has been found to inhibit the Akt/mTOR signaling pathway, leading to the suppression of cell proliferation and migration." (PMID 37359381, 2023). "Ruthenium–phloretin complex regulated the PI3K/Akt/mTOR pathway with MMP9 to inhibit tumor invasion and arrest breast cancer progression." (PMID 37701204, 2023). "In murine breast cancer, we previously demonstrated that EC’s antiproliferative effect is related to regulating AMPK and Akt/mTOR signaling pathways." (PMID 37687058, 2023). "For instance, miR‐100‐loaded Exos can efficiently regulate the mTOR/HIF‐1α/VEGF pathway and blunt angiogenesis in breast cancer cells." (PMID 37156724, 2023). "DPP-4 knockdown significantly promoted the levels of CXCL12, CXCR4, phospho-mTOR, and HIF-1α in breast cancer cell lines." (PMID 37760498, 2023).
breast cancer (continued). "In contrast, UBE2C knockdown leads to inhibition of proliferation and invasion in breast cancer cells, as well as a decrease of p-AKT, p-mTOR, and hypoxia-inducible factor 1-α (HIF-1α) and an increase of phosphorylated phosphatase and p-PTEN levels." (PMID 37958776, 2023). "In order to improve ER+ breast cancer treatment, a combination of endocrine therapies with other compounds, such as CDK4/6 inhibitors, mTOR inhibitors, PI3K inhibitors, and AR antagonists, are under investigation." (PMID 37173983, 2023). "As shown in breast cancer models, the combination of a CDK 4/6 inhibitor with a PI3K/mTOR inhibitor have produced synergistic treatment effects." (PMID 37326340, 2023). "In the HER2+ breast cancer subtype, preclinical evidence has shown that inhibitors of the PI3K/AKT/mTOR pathway can enhance the antiproliferative activity of anti-HER2 therapies and/or overcome the acquired resistance to these agents." (PMID 37469415, 2023). "Meanwhile, the target genes of miRNAs in module 4 were mainly enriched in MAPK signaling pathway, Breast cancer, PI3K-Akt signaling pathway, Axon guidance, mTOR signaling pathway, FoxO signaling pathway, and Neurotrophin signaling pathway." (PMID 36911413, 2023). "Regarding the mTOR/PI3K pathway, mTOR inhibitors are approved for the treatment of renal cell, neuroendocrine, and hormone-positive/HER-2-negative advanced breast cancer." (PMID 37193984, 2023). "We found KK-LC-1 was enriched in the “Pathway in Cancer”, “Breast Cancer Pathway”, “Mammary Gland Epithelium Development”, “Wnt Beta-catenin Pathway”, “PI3K/AKT Signaling Pathway, “and “AKT, mTOR”." (PMID 36895039, 2023). "Patients with obesity also have higher insulin levels, leading to increased IGF-1 in breast cancer cells, which activates the PI3K/AKT/mTOR and RAS/RAF/MAPK signaling pathways that result in endocrine therapy resistance." (PMID 37173991, 2023). "Curcumin suppressed breast cancer cell growth and triggered G2/M phase cell cycle arrest and apoptosis, which could be linked to decreased CDC25 and CDC2 protein levels, increased P21 protein levels, suppression of Akt/mTOR phosphorylation, and stimulation of the mitochondrial apoptotic pathway." (PMID 36836717, 2023). "Curcumin has been reported to interfere with the phosphorylation of Akt and the mechanistic target of rapamycin (mTOR) in MCF7 and T47D breast cancer cells." (PMID 37176840, 2023). "In the context of breast cancer, it is well known that specific kinases such as HER2 receptor tyrosine kinase, PI3K, Akt, and mTOR are involved in breast cancer pathogenesis and progression." (PMID 37894581, 2023). "C3 alone also achieves therapeutic effects on breast cancer by binding to IGF-1R, Akt, and mTOR, reducing the primary focus and metastatic load in tumor-bearing mice." (PMID 37749560, 2023). "In breast cancer, hepatocarcinoma, and gliomas, the anti-survival effects of 5-MOP were attributed to PI3K downregulation, as well as its downstream AKT and mTOR effectors." (PMID 37958539, 2023). "Deregulation of the mTOR pathway (such as the overexpression of S6K1 and EIF4EBP1) is often found in human cancers (such as breast cancer) and promotes cell proliferation." (PMID 37686205, 2023). "The role of MUC1-C is more powerful and can be involved in several classical downstream pathways of breast cancer, including the PI3K/AKT/mTOR pathway." (PMID 36895039, 2023). "In this study, through extensive molecular characterization of gastrointestinal and breast cancer cells, we found that SMYD3 is part of a multiprotein complex that is involved in DNA damage response and also comprises AMPK and mTOR." (PMID 37998381, 2023). "In breast cancer cells, GPR176 silencing was shown to ameliorate proliferation and induce apoptosis by either inactivating PTEN/PI3K/Akt/mTOR or decreasing Bcl-2/Bax." (PMID 37079213, 2023).
breast cancer (continued). "Existing research has suggested that inhibiting PI3K/AKT/mTOR and EMT markers can suppress the invasion and migration of cancer cells in lung cancer, liver cancer, as well as breast cancer." (PMID 36910848, 2023). "In breast cancer, silencing OGT expression reduces mTOR expression and impairs cancer cell proliferation." (PMID 37838167, 2023). "Across different breast cancer subtypes, the most common abnormalities are aberrations in the PI3K/AKT/mTOR pathway." (PMID 36244040, 2023). "Lehmann and colleagues discovered that the IC50 of a PI3K/mTOR inhibitor, NVP–BEZ235, for MDA–MB–231 was lower than that for HCC–1937, and that breast cancers of M and MSL subtypes were more sensitive to PI3K/mTOR inhibitor treatment." (PMID 36672419, 2023). "However, mTOR inhibitors may also induce breast cancer to evade drug effects." (PMID 37637052, 2023). "Neurensin‐2 (NRSN2) also promotes breast cancer metastasis by activating the PI3K/AKT/mTOR and NF‐κB signaling pathways, and melittin suppresses EGF‐induced cell motility and invasion by inhibiting the PI3K/Akt/mTOR signaling pathway in breast cancer cells." (PMID 37249285, 2023). "Magnoflorine induces apoptosis and autophagy by inhibiting AKT/mTOR and promoting p38 MAPK signaling pathways, and enhances the sensitivity of breast cancer cells to doxorubicin (DOX) (Wei, Xiaojun & Peilong, 2020)." (PMID 36751636, 2023). "Camizestrant, a next-generation oral SERD, shows promise in preclinical models of ER+ breast cancer alone and in combination with CDK4/6 and PI3K/AKT/mTOR inhibitors to address endocrine resistance, a current barrier to treatment." (PMID 37725704, 2023). "FLI1 has been reported to influence PI3K/AKT signaling in breast cancer, and EWS-FLI1 fusion gene enhances PI3K/AKT/mTOR signaling in Ewing sarcoma." (PMID 36814284, 2023). "Therefore, anti-HER2 therapy alone may not be adequate treatment for those patients with HER2+ breast cancer harboring a PIK3CA-activating mutation that are associated with a constitutive activation of the PI3K/AKT/mTOR pathway." (PMID 37469415, 2023). "The combination of PI3K/AKT/mTOR and CDK4/6 inhibitors has been studied in preclinical models and is still under research in clinical trials in patients with advanced breast cancer (NCT02389842), lung cancer and other cancers (NCT03065062)." (PMID 36792625, 2023). "The combination of BYL-719 plus everolimus, an mTOR inhibitor, has been studied in PIK3CA mutant breast cancer cell lines previously and was reconfirmed through this study." (PMID 36900375, 2023). "In breast cancer, TAM-secreted CCL2 promotes an endocrine resistance by activating the PI3K/AKT/mTOR signaling pathway." (PMID 37272931, 2023). "The authors demonstrated that the levels of mTOR, phospho-m-TOR, and mitogen-activated kinase p-P70S6K proteins decreased after metformin treatment of breast cancer cells resistant to tamoxifen." (PMID 37444428, 2023). "The G2/M cell cycle arrest and mTOR/PI3K/AKT were observed in lung cancer cells, and in breast cancer via ATM mediated damage." (PMID 37887406, 2023). "In breast cancer cells, mTORC1 activates SREBP-2 to promote lipogenesis, cell growth, proliferation and survival that can be ablated with mTOR inhibitors, linking mTORC1 control to SREBP-2 signaling." (PMID 37986175, 2023). "Trastuzumab resistance in HER2-positive breast cancer involves increased EGFR and IGF1R signals as well as dysregulation of the PTEN/PI3K/AKT/mTOR pathway." (PMID 38114573, 2023). "The mTOR/AKT pathway functions centrally in cell proliferation and growth and is frequently overactivated in breast cancer." (PMID 37701204, 2023).